GLIPR1L2 (GLIPR1 like 2)
Synonyms: MGC39497
Tractability: Antibody: UniProt predicts a signal peptide or a membrane-spanning region.
Gene: Protein-coding gene on chromosome 12 (75,391,089 to 75,432,688, forward strand). Ensembl gene ENSG00000180481.
Subcellular location: Membrane
Subcellular location (Human Protein Atlas): Golgi apparatus; Vesicles
Gene Ontology:
Cellular component: membrane
Genetic constraint (gnomAD): Loss-of-function variants: 18 observed, 21.6 expected, observed/expected ratio (o/e) 0.83, 90% interval 0.57 to 1.24. The upper end of that interval is the gene's LOEUF score, 1.24, which puts it in group 5 of 6, group 1 being the genes least tolerant of losing a copy. Missense variants: 337 observed, 335.02 expected, observed/expected ratio (o/e) 1.01, 90% interval 0.92 to 1.1. Synonymous variants: 118 observed, 120.99 expected, observed/expected ratio (o/e) 0.98, 90% interval 0.84 to 1.14.
Homologues: Orthologues: chimpanzee GLIPR1L2 (98% identical), rabbit GLIPR1L2 (72% identical), macaque GLIPR1L2 (67% identical), pig GLIPR1L2 (66% identical), dog GLIPR1L2 (64% identical), mouse Glipr1l2 (60% identical), rat Glipr1l2 (59% identical), zebrafish glipr1a (31% identical), zebrafish glipr1b (22% identical), Drosophila melanogaster CG42564 (17% identical), Caenorhabditis elegans scl-19 (14% identical), Caenorhabditis elegans scl-6 (14% identical), and 46 more. Paralogues in human: GLIPR1 (30% identical), GLIPR1L1 (25% identical), CRISPLD2 (22% identical), CRISPLD1 (21% identical), CRISP3 (19% identical), CLEC18B (19% identical), CRISP2 (19% identical), CLEC18A (18% identical), CLEC18C (18% identical), CRISP1 (18% identical), R3HDML (17% identical), PI15 (17% identical), and 1 more.
Diseases named in the same sentence as GLIPR1L2 in open-access papers:
GLIPR1L2 is named in the same sentence as 4 diseases in open-access papers, as found by Europe PMC text mining. Sharing a sentence is not in itself a finding about the gene and the disease. The quoted sentences say what the papers report.
glioma (1 paper, 2017). A benign or malignant brain and spinal cord tumor that arises from glial cells (astrocytes, oligodendrocytes, ependymal cells). "For intra-pair difference in zFVC (log-ΔzFVCIP), ten sites with a p value < 10−5 were identified, with the most significant probe identified as cg02071292 annotated to GLI (glioma) pathogenesis-related 1-like 2 (GLIPR1L2) with a p value = 7.14 × 10−8 (FDRadjp value = 0.03)." (PMID 29299071, 2017).
lung carcinoma (1 paper, 2024). "GLI pathogenesis-related 1 functions as a tumor suppressor in lung cancer, and during lung tumorigenesis, the expression of GLIPR1L2 is downregulated." (PMID 38791918, 2024).
cancer (2 papers, 2023 to 2024). A tumor composed of atypical neoplastic, often pleomorphic cells that invade other tissues. "GLIPR1L2 (average methylation 19%, p = 0.008) plays a significant role in cancer and immune defense." (PMID 38791918, 2024). "METTL7A has protein interactions with cancer-related genes BCAS1 and GLIPR1L2, as well as post-transcriptional regulatory genes METTL8 and DDX55." (PMID 37547717, 2023). "CAPS2 (Calcyphosine 2) (average methylation 26%, p = 0.005) and GLIPR1L2 (GLI pathogenesis-related 1) (average methylation 30%, p = 0.008), both were previously discussed in the group due to hypomethylation in PD-L1 high-expressing carcinomas." (PMID 38791918, 2024).
tumor (2 papers, 2017 to 2024). "Three probes identified for level of FVC were located in GLIPR1L2 gene (lowest p value = 7.14 × 10−8), involved in innate immunity and tumour-suppressor/pro-oncogenic mechanisms." (PMID 29299071, 2017). "Hypomethylated genes and promoters in this group seem to lose their tumor-suppressing effects (IFITM3 and GLIPR1L2) and perhaps show a reduction in oncogene activity (CAPS2)." (PMID 38791918, 2024).